EPO (erythropoietin)
Diseases named in the same sentence as EPO in open-access papers (continued):
Sharing a sentence is not in itself a finding about the gene and the disease.
chronic kidney disease (continued). "The use of guideline-directed medical therapy for heart failure (HF) as well as erythropoietin-stimulating agents for the management of anemia in chronic kidney disease (CKD) has not been shown to be as effective in patients with CRAS as in isolated conditions." (PMID 37767373, 2023). "In the uremic status of end-stage renal disease (ESRD), the lysine residue of erythropoietin (EPO) is carbamylated and decreases in activity, resulting in the production of non-functional EPO, which leads to hypoxemia." (PMID 34638916, 2021). "Similarly, sensitivity analyses and subgroup analyses based on chronic kidney disease (CKD) status yielded consistent results, indicating that the prognostic impact of EPO in sepsis is independent of hypoxia and renal function." (PMID 40114237, 2025). "Carbamylated darbepoetin (recombinant human erythropoietin) or darbepoetin (100 ng/ml) could decrease telomere shortening and senescence induced by TNF-α and uremic serum in EPCs from non-dialysis chronic kidney disease patients." (PMID 34712416, 2021).
iron deficiency (335 papers, 2005 to 2026). "As expected from prior literature, patients with PV showed lower ferritin, TSI, and EPO levels together with higher Hb and Hct values, consistent with a phenotype of expanded erythropoiesis in the setting of functional iron deficiency." (PMID 41577837, 2026). "The microcytic anemia observed can lead to hemolysis due to RBC deformation, iron deficiency from competition in duodenal absorption, and renal anemia because of reduced erythropoietin (EPO) production." (PMID 40423428, 2025). "Future research should delve deeper into key biomarkers, including HIF-1α, VEGF, EPO, iron deficiency markers, and hepcidin levels." (PMID 39940380, 2025). "Red blood cells (RBCs) play a critical role in sepsis, with decreased RBC count seen in this condition due to factors like functional iron deficiency, decreased erythropoietin synthesis, infection, and inflammation." (PMID 39847548, 2025). "The etiology of renal anemia is multifactorial and includes inappropriately low erythropoietin (EPO) production, absolute and functional iron deficiency, and shortened red blood cell (RBC) lifespan." (PMID 39568068, 2025). "Similar studies pointed out that low Hb concentrations likely due to erythropoietin or iron deficiency potentially exacerbate oxidative stress and accelerate brain aging." (PMID 39924931, 2025). "This is primarily due to red blood cell turnover in this population, often resulting from iron deficiency and reduced erythropoietin production due to uraemic toxins, which in turn affects the accuracy of HbA1c as an indicator of long-term glucose levels." (PMID 40625696, 2025). "PTA is highly associated with the worsening of renal function, iron deficiency, infections, and low levels of EPO." (PMID 41020856, 2025). "Functional iron deficiency lowers hypoxia-inducible factor levels, reducing the production of erythropoietin." (PMID 39926283, 2025). "The mechanisms are decreased EPO production, iron deficiency, inflammation, and shortened erythrocyte lifespan." (PMID 41040470, 2025). "Anemia in CKD arises from multifactorial etiologies, including reduced endogenous erythropoietin synthesis, iron deficiency, and inflammation-induced hepcidin." (PMID 41353335, 2025). "Conversely, in iron deficiency, as in hypoxic conditions or EPO-mediated signaling pathways, HAMP synthesis in the nucleus is reduced." (PMID 41515226, 2025). "HIF-PH inhibitors improve functional iron deficiency by facilitating the section of endogenous erythropoietin and suppressing the synthesis of hepcidin." (PMID 41353335, 2025). "Of particular significance, dogs with iron deficiency had higher erythropoietin and lower thrombopoietin concentrations than dogs with normal serum iron." (PMID 41463898, 2025). "Anisocytosis can be caused by inflammation, nutritional status, iron deficiency, inadequate erythropoietin production, or oxidative stress." (PMID 41323008, 2025). "EPO levels have also been shown to be increased in this population, secondary to iron deficiency in its active metabolic pool." (PMID 38696124, 2024). "Current medical research suggests that the main causes of this disease are reduced production of erythropoietin (EPO), iron deficiency, and metabolic imbalances." (PMID 39724079, 2024). "Anemia is a common complication of CKD, largely driven by reduced erythropoietin production and iron deficiency, which worsens as kidney function declines." (PMID 39595570, 2024). "Several factors can explain this, including iron deficiency, defective erythropoietin production, decreased bone marrow response to erythropoietin, and defective iron release from the reticuloendothelial system." (PMID 39136015, 2024). "Factors that have been reported to concurrently increase FGF23 transcription and post-translational cleavage, resulting in the disproportionate cellular secretion of FGF23 fragments, include iron deficiency, erythropoietin, and inflammation." (PMID 37752381, 2024).
iron deficiency (continued). "Similar to iron deficiency, both endogenous and exogenous EPO increases transcription through the cleavage of FGF23." (PMID 38732094, 2024). "The pathogenesis of renal anemia is primarily associated with a relative deficiency of EPO in the body, iron deficiency, shortened RBCLS, and chronic inflammation." (PMID 39685563, 2024). "Treatment strategies for renal anemia in CKD will have evolved, focusing on addressing both EPO and iron deficiencies and considering the broader spectrum of metabolic disturbances." (PMID 38612557, 2024). "Inflammation, which persists as long as the anemic condition continues, blunts the responsiveness of erythropoietin and causes functional iron deficiency." (PMID 36793527, 2023). "Renal anemia is associated with dysregulation of oxygen sensing by the malfunctioning kidneys, leading to inadequate synthesis of erythropoietin (EPO), iron deficiency, and inflammation." (PMID 37936193, 2023). "If the EPO response is blunted in anemic patients compared to younger patients with iron deficiency, this would suggest the presence of EPO resistance in the anemic group." (PMID 37240288, 2023). "On the one hand, there are conditions, including iron deficiency, inflammation, and increased erythropoietin (EPO), that stimulate FGF23 transcription and cleavage, resulting in high cFGF23 but normal iFGF23 concentrations." (PMID 37808399, 2023). "Upregulated erythropoietin (EPO) can inhibit hepcidin mRNA under conditions such as hypoxia or an iron deficiency." (PMID 36576329, 2023). "On the contrary, hepcidin is expressed more than in wild-type mice, suggesting that the increase in EPO is invalid and is the consequence of iron deficiency in the bone marrow." (PMID 36978814, 2023). "In the setting with normal kidney function, iron deficiency, and EPO increase the production and cleavage of FGF23." (PMID 36831276, 2023). "This is surprising taking into account that, for an adequate action of erythropoietin treatment, previous iron supplementation is necessary, especially in cases with a preexisting iron deficiency." (PMID 38137939, 2023). "Iron deficiency enhances erythropoiesis by increasing renal erythropoietin (EPO) production and erythroblastic EPO sensitivity via the genetic loss of the EPO receptor (EPOR) partner transferrin receptor 2 (TfR2)." (PMID 37108056, 2023). "Recent research revealed an important bidirectional crosstalk between FGF23, known as a major regulator of phosphate homeostasis, with iron deficiency and EPO production." (PMID 36831276, 2023). "The pathogenesis of anaemia in CKD is multifactorial, but the impaired erythropoietin production and iron deficiency (iron-deficiency anaemia, IDA) are the primary mechanisms involved." (PMID 36233688, 2022). "The leading cause of AOP is iatrogenic blood loss from phlebotomy; additional factors include impaired erythropoietin (EPO) production, shortened red blood cell life span, and iron deficiency." (PMID 36010080, 2022). "Hepcidin is stimulated by iron overload and inflammation (specifically interleukin-6) and inhibited by iron deficiency, hypoxia, and erythropoietin-stimulated erythroblasts." (PMID 35795334, 2022). "Correspondingly, Vitamin D deficiency stimulates the immune cells to produce cytokines, resulting in higher hepcidin levels and consequent functional iron deficiency and erythropoietin resistance." (PMID 35795334, 2022). "The management of posttransplant iron deficiency is complicated by uncertainty about the target hemoglobin, iron deficiency measures such as ferritin or transferrin saturation, and the role of erythropoietin." (PMID 35795334, 2022). "There are several and complex mechanisms behind heart failure related iron deficiency and at least renal failure, bone marrow resistance to erythropoietin, chronic inflammation, medication use, and hematinic deficiencies have been found so far." (PMID 35442992, 2022).
iron deficiency (continued). "The causes of renal anemia include erythropoietin (EPO) deficiency, iron deficiency, disturbance of iron metabolism in the body and resistance of the EPO signaling pathway." (PMID 36225579, 2022). "Nevertheless, we observed that in this cohort of HC patients in maintenance treatment, EPO was inappropriately high, in many cases at the levels observed in iron deficiency conditions." (PMID 36034093, 2022). "Although it results from a complex interplay of factors, erythropoietin deficiency due to decreased synthesis by renal peritubular capillary interstitial cells and iron deficiency play a predominant role." (PMID 35795334, 2022). "Among these mechanisms, EPO deficiency and functional iron deficiency are associated with the HIF signaling pathway and have recently begun receiving attention." (PMID 33478025, 2021). "In severe iron deficiency, the bone marrow is exposed to high EPO levels, favoring the erythroid lineage at the expense of platelet production." (PMID 34557594, 2021). "The most common causes include a decrease in erythropoietin (EPO) synthesis, iron deficiency (IDA), and chronic inflammation." (PMID 34442028, 2021). "In CKD patients, iron deficiency and increased blood erythropoietin (EPO) levels can stimulate the expression of FGF23." (PMID 34901023, 2021). "Both inflammation and functional iron deficiency stimulate Fgf23 transcription indirectly through the production of erythropoietin (EPO)." (PMID 33716961, 2021). "Iron is required for an adequate erythropoietic response to EPO, and in anemic conditions having iron deficiency corrected allows lower exogenous EPO supplies." (PMID 33842503, 2021). "This leads to inhibition of duodenal iron absorption and contributes to systemic iron deficiency, iron deficiency for erythropoiesis, and resistance to endogenous exogenous erythropoietin." (PMID 33918997, 2021). "When the systemic iron deficiency in mask mice is corrected by placing them on carbonyl iron diet, their red blood cell parameters normalize and administration of EPO results in a further increase of both hemoglobin and hematocrit." (PMID 33800732, 2021). "Insufficient production of erythropoietin and iron deficiency is the main cause of anemia in maintenance HD patients." (PMID 34126941, 2021). "The most important adverse events reported with erythropoietin administration are arterial hypertension, cerebral convulsion/hypertensive encephalopathy, thromboembolism, iron deficiency and influenza-like syndrome." (PMID 34832856, 2021). "Functional iron deficiency is a common cause of suboptimal hemoglobin response to EPO analogue therapy." (PMID 34830468, 2021). "Erythropoietin levels, when measured, were elevated, whereas only some patients also showed iron deficiency and elevated ferritin." (PMID 33525735, 2021). "In general, relative iron deficiency is more common and is closely related to the upregulation of inflammatory cytokines and impaired tissue responsiveness to erythropoietin." (PMID 32454794, 2020). "The administration of the pan-histone deacetylase inhibitor (pan-HDAC-panobinostat) abrogates hepcidin inhibition by iron deficiency or erythropoietin administration in mice." (PMID 32456060, 2020). "Iron deficiency, erythropoietin hyporesponsiveness, haemolysis, and greater intradialytic fluid extraction were related to shortened RBC age." (PMID 32993543, 2020). "This decrease in EPO production is associated with true iron deficiency related to blood loss due to uremic enteropathy and hemodialysis treatment aggravated by iron-restricted anemia (linked to high levels of hepcidin)." (PMID 32899941, 2020). "In case of side effects, intolerance or inadequate compliance to oral therapy, poor gastrointestinal iron absorption, erythropoietin administration, severe iron deficiency, and chronic blood loss, intravenous iron replacement is indicated." (PMID 32481481, 2020).
iron deficiency (continued). "It is well established that the main cause of renal anemia is an inadequately low renal erythropoietin (Epo) synthesis combined with functional iron deficiency." (PMID 33363152, 2020). "Although renal anemia is predominantly caused by an impaired EPO production, several other factors (e.g., iron deficiency) can worsen erythropoiesis in renal patients." (PMID 32899941, 2020). "A reticulocyte index ≥2 is related to blood loss or hemolysis; if lower than 2, this indicates bone marrow failure, iron deficiency, or poor erythropoietin production." (PMID 32481481, 2020). "When iron deficiency occurs, EPO upregulates TfR expression and thereby increases the sTfR concentration in the serum." (PMID 32320096, 2020). "Inhibition of iFGF23 signaling with rh-cFGF23 in CKD mice resulted in decreased erythroid cell apoptosis, upregulation of renal and BM HIF1α and subsequent EPO mRNA expression, elevated serum EPO levels and amelioration of iron deficiency." (PMID 30971944, 2019). "Currently, the clinical implications of iron deficiency and high EPO levels in the general population, as well as the potential downstream role for FGF23, are unclear." (PMID 31170159, 2019). "Iron deficiency and elevated levels of EPO were major determinants of FGF23 levels, to a greater extent than more established determinants such as renal function and serum calcium, PTH, and phosphate." (PMID 31170159, 2019). "To date, clinical implications of iron deficiency and high EPO levels in the general population, and the potential downstream role of FGF23, are unclear." (PMID 31170159, 2019). "Lower EPO concentrations were associated with rapid eGFR decline, especially in patients with iron deficiency (P for interaction = 0.01)." (PMID 31619722, 2019). "On the other hand, iron deficiency partially attenuated the induction of splenic TFR2 protein by EPO, suggesting that both liver and splenic TFR2 proteins are to some extent posttranscriptionally regulated by iron availability." (PMID 30958854, 2019). "In conclusion, we have shown that functional iron deficiency and higher EPO levels are strongly associated with increased all-cause mortality in the general population." (PMID 31170159, 2019). "In this study, we found that functional iron deficiency and higher EPO levels were each associated with an increased risk of death in the general population." (PMID 31170159, 2019). "Functional iron deficiency and EPO were associated with an increased risk of death in the general population, and FGF23 explained a substantial part of these associations." (PMID 31170159, 2019). "The main marker of erythrocyte turnover is the hormone erythropoietin, which was higher in XX genotypes, suggesting that the small number of XX runners with iron deficiency were also influenced by increased erythrocyte turnover after race." (PMID 31244673, 2019). "The current findings suggest that FGF23 is important in the pathophysiology of iron-deficiency–and EPO-mediated mortality in the population." (PMID 31170159, 2019). "Erythropoietin (EPO) is used to treat functional iron deficiency, and blood transfusion is restricted to refractory patients or in life-threatening emergency situations." (PMID 31614529, 2019). "It further shows that iron deficiency and EPO administration have an additive effect on the downregulation of liver Hamp expression." (PMID 30958854, 2019). "Some CKD patients with iron deficiency show blunted response or even don’t respond to a single EPO injection." (PMID 30108502, 2018). "This is likely to reflect the greater severity of erythropoietin dysregulation in patients with Chuvash polycythemia, in whom frequent venesection is required, with consequent iron deficiency." (PMID 28400504, 2017).